GPX3 (glutathione peroxidase 3)
Diseases named in the same sentence as GPX3 in open-access papers (continued):
Sharing a sentence is not in itself a finding about the gene and the disease.
diabetes (continued). "Moreover, a red guava-containing diet can increase the expression of GPx3, further improving diabetes-induced oxidative damage, and can increase ACO expression, which improves lipid metabolism and reduces lipid levels in the blood." (PMID 26703532, 2015). "However, experimental studies on animals and humans report that in the early phase of diabetes, GPX3 may initially increase as a compensatory mechanism against rising reactive oxygen species (ROS), but as oxidative stress becomes chronic, this mechanism depletes, and GPX3 levels decline." (PMID 40299518, 2025). "However, GPx3 may still hold potential as an indicator of progression to diabetes." (PMID 38791447, 2024). "A recent report in patients with and without diabetes with an average reduction in body weight of 25% after bariatric surgery, compared with 9% loss with lifestyle change, had a significant decrease in mRNA expression of GPx-3 in subcutaneous and visceral adipose tissue." (PMID 31817851, 2019). "According to this, our results revealed an increase of GPx-3 in the serum of diabetes patients with CVD compared to those without CVD and controls." (PMID 25923078, 2015). "Type 2 diabetes mellitus patients with cardiovascular disease showed higher expression of plasma retinol binding protein and glutathione peroxidase-3 compared to those without cardiovascular disease and non-diabetic controls." (PMID 25923078, 2015). "Diabetic kidneys had increased transcript and membrane-bound protein levels of Nox4, the renal-specific generator of cytosolic reactive oxygen species (ROS) and reduced expression of SOD2, UCP2, GPX3, NQO1, and CAT." (PMID 23149823, 2013). "In addition, we did not include patients without diabetes to corroborate the sex differences in GPx-3 activity." (PMID 31817851, 2019).
COVID-19 (18 papers, 2020 to 2025). A disease caused by infection with severe acute respiratory syndrome coronavirus 2. "Of all the examined polymorphisms, we found significant association with the risk of developing severe forms of COVID-19 for GPX3 rs8177412 variant genotype (OR = 2.42, p = 0.032)." (PMID 38003341, 2023). "Emerging genetic evidence suggests that a specific GPx3 variant (rs8177412) may be associated with an increased risk of developing severe COVID-19 and cardiovascular complications in recurrent cases." (PMID 40429727, 2025). "Additionally, Marko Markovic revealed a significant association between the GPX3 rs8177412 variant genotype and the risk of developing severe forms of COVID-19, suggesting that GPX3 is a complementary diagnostic tool for predicting the disease course." (PMID 38927092, 2024). "In contrast, GPX3 was decreased in COVID-19 patients with comorbidities—consistent with previous reports—which revealed lower glutathione peroxidase activity due to the SARS-CoV-2 infection as well as Epstein–Barr virus infection in diabetic patients." (PMID 38672194, 2024). "Nuclear factor erythroid-2 like 1 (NFE2L1) and glutathione peroxidase 3, which regulate oxidative stress and inflammatory responses, were upregulated following COVID-19 (P < 0.001 and P = 0.010, respectively)." (PMID 37019821, 2023). "Another glutathione peroxidase analyzed in our study, GPX3, has just recently been investigated in critically ill COVID-19 patients as an important factor in the interplay between inflammation and oxidative stress." (PMID 35624818, 2022). "Although initial results obtained in our study have shown that the presence of at least one GPX3*C allele reduces the risk of COVID-19, such significant effect was not achieved when adjusted analysis was performed." (PMID 35361071, 2022). "The examined polymorphisms of Nrf2, SOD2, GPX1 and GPX3 in our study also did not have association with severity of COVID-19 (Table A1)." (PMID 35361071, 2022). "However, 88% of the COVID-19 patients still had an inadequate Se status based on the Se requirement for optimization of GPx3 activity (i.e., [Se] > 90 μg L−1) at that time." (PMID 34684306, 2021). "In this manuscript, we report that patients suffering from COVID-19 display a deficiency in the essential trace element Se in blood, along with low concentrations of the Se transporter SELENOP and low enzymatic activity of the secreted GPx3." (PMID 32708526, 2020). "Hence, it could be speculated that recovered COVID-19 patients, who are carriers of referent GPX1 or GPX3 alleles, are more prone to developing LV diastolic impairment." (PMID 37373377, 2023). "COBL, GPX3 and SOCS3 were lower in the early and late secretory phase in women with COVID-19, whereas DOCK2 and SLC2A3 were unchanged." (PMID 38372528, 2024). "This in silico model predicted that five genes important for embryo implantation were affected by COVID-19 (down-regulation of COBL, GPX3 and SOCS3, and up-regulation of DOCK2 and SLC2A3)." (PMID 38372528, 2024). "Another study conducted by the same research team on 33 COVID-19 patients suggested remarkably lower levels of serum selenium, SELENOP, and glutathione peroxidase-3 in deaths comparing to discharges." (PMID 34739678, 2022). "Additionally, patients with severe COVID-19 and acute respiratory distress syndrome (ARDS) admitted to intensive care units (ICUs) exhibited reduced serum GPx3 activity, which was significantly improved after 10–14 days of selenium supplementation." (PMID 40429727, 2025). "However, a recent study showed that daily intravenous selenium (1 mg Sel) in a cohort of COVID-19 patients with severe ARDS for a total of two weeks elevated their selenoprotein P and GPX3 levels." (PMID 37888066, 2023). "A direct comparison of Se status in COVID-19 patients to reference values for the activity of GPx3 as a biomarker was not possible, as GPx3 had not been determined in the samples of the large reference cohort from the EPIC study." (PMID 32708526, 2020).
ovarian carcinoma (18 papers, 2006 to 2025). A malignant neoplasm originating from the surface ovarian epithelium. "It has been reported that GPX3 was highly expressed in ovarian cancer cells and was associated with platinum resistance." (PMID 36845676, 2023). "We observed that GPX3, an extracellular antioxidant, was significantly upregulated in the high-risk group, which supports the extracellular antioxidant defense of ovarian cancer cells and contributes to the progression of ovarian cancer." (PMID 38226979, 2024). "By eliminating extracellular oxidants like H2O2, GPX3 is crucial for ovarian cancer cells to thrive in ascites." (PMID 38226979, 2024). "Several studies reported that in patients with high-grade ovarian serous carcinoma this response is dysregulated and low levels of glutathione peroxidase 3 were recorded in patients with metastatic or relapsed ovarian cancer." (PMID 36611458, 2023). "A previous study reported that in the HGSA subtype of ovarian cancer, there is a distinct separation between tumors with high and low GPX3 expression." (PMID 38042786, 2023). "GPX3 is essential for the survival of HGSA ovarian cancer cells in the ascites tumor microenvironment, and it acts as a protective factor against external oxidative stress factors." (PMID 38042786, 2023). "GPX3 was found to be expressed higher in clear cell type ovarian adenocarcinoma than in other types of ovarian cancer." (PMID 36845676, 2023). "Previous studies related the presence of the GPX3*C (rs8177412) variant allele with lower transcriptional activity and, thus, reduced intracellular expression of GPX3 enzyme in almost all examined tumor tissue samples, except in the case of ovarian cancer." (PMID 35205816, 2022). "GPX3 shows an important protective and adaptation function in ovarian cancer cellular survival in the ascites tumor environment, especially in high grade serous adenocarcinoma." (PMID 33987033, 2021). "GPx3 is essential for the survival of ovarian cancer cells in the ascites tumor environment and protects against extracellular oxidative stressors, suggesting that GPx3 is an important adaptation for metastasis." (PMID 34926458, 2021). "Knock-down of GPx3 in ovarian cancer cells inhibits anchorage-independent survival and enhances cell death in response to high dose ascorbate, a pro-oxidant at mM doses." (PMID 32781581, 2020). "This suggests that GPx3 protects ovarian cancer cells during metastatic progression within malignant ascites, and in response to exogenous sources of ROS." (PMID 32781581, 2020). "Since most ovarian cancer cases are diagnosed in postmenopausal women, we next compared the levels of GPX3 between controls and patients such that we included only women ≥ 50 years of age in each group." (PMID 22017790, 2011). "A number of recent studies in clear cell ovarian cancer tissues conducted by others have identified a higher expression of GPX3 when compared to control cells and in other epithelial ovarian cancer histologies." (PMID 22017790, 2011). "In other tissues, similar redox–SMAD interactions are at play: in ovarian cancer, GPx3 helps maintain levels of GDF15 (a TGF-β family member) and supports tumor growth, whereas knocking down GPx3 in ID8 cells lowers GDF15, delays ascites onset, and markedly reduces omental tumors in mice." (PMID 41009046, 2025). "Further, GPx3’s regulation of GDF15 expression could enhance ovarian cancer immune therapies by targeting extracellular GPx3 or GDF15." (PMID 41009046, 2025). "In addition, GPX3 plays a beneficial role in ovarian cancer cell clonogenicity and survival, which acts as a key measure of anchorage-independent cell survival." (PMID 38226979, 2024). "Intriguingly, GPX3 has been reported to be upregulated in clear cell ovarian cancer tissues and thus may have implications in chemotherapeutic resistance." (PMID 22017790, 2011).
ovarian carcinoma (continued). "Exclusively associated to cluster three (magenta, mucinous tumors) are the connective tissue growth factor (CTGF) which will be discussed in context of present alcohol consumption as well as the glutathione peroxidase 3 (GPX3) which was reported to be overexpressed in ovarian cancer." (PMID 17181856, 2006). "Thus, the inhibition of GPX3 in ovarian cancer cells may hold potential for the development of novel anti-tumor drugs in the future." (PMID 38226979, 2024). "Furthermore, decreased GPX3 expression could inhibit clonogenicity and anchorage-independent cell survival in ovarian cancer progression." (PMID 32292720, 2020). "Thus, while a number of other studies have examined GPX3 levels in a broad array of cancer, these studies provide the first analysis of this candidate biomarker in epithelial ovarian cancer, specifically, the serum of women with papillary serous ovarian cancer." (PMID 22017790, 2011). "Given that papillary serous epithelial ovarian cancer represents the majority of ovarian tumors and that no previous studies have examined serum GPX3 levels in women with this histology of ovarian cancer, we therefore hypothesized that GPX3 may represent a novel biomarker for this disease." (PMID 22017790, 2011). "In the TCGA and GTEx databases, we found that GPX3 mRNA expression was downregulated in various types of cancers, including BRCA, COAD, LUAD, ovarian cancer (OV), kidney renal clear cell carcinoma (KIRC), and endometrial cancer (EC)." (PMID 36845676, 2023). "GPX3 is considered the only secretory protein among GPX family of the proteins and its upregulation promotes the ovarian cancer progression by modulating tumor microenvironment redox condition." (PMID 32763516, 2020). "Lower Se status and glutathione peroxidase 3 (GPX3) activity are shown to contribute in the progression of neoplastic diseases of female reproductive system including endometrial and ovarian cancers." (PMID 31835711, 2019). "While our studies clearly define decreased serum GPX3 levels in women with ovarian cancer, we are not able to distinguish whether the decrease may represent a risk factor for the development of the cancer or simply represents a systemic response to the disease." (PMID 22017790, 2011).
hepatocellular carcinoma (17 papers, 2014 to 2025). A malignant tumor that arises from hepatocytes. "GPX3 modulates the ROS level in malignant melanoma, hepatocellular carcinoma, and colitis-associated carcinoma and consequently inhibits tumor cell proliferation." (PMID 37087463, 2023). "Lower GPX3 levels in the plasma and tumor tissue of non-small-cell lung cancer, glioblastoma, hepatocellular carcinoma and colorectal carcinoma have been linked to selenium deficiency and increased lipid peroxidation, supporting the notion that loss of GPX3 contributes to oxidative stress." (PMID 33050144, 2020). "In hepatocellular carcinoma, it was found that cells immediately adjacent to tumor tissues also display decreased GPx3 expression, with the authors suggesting that pre-cancerous lesions may already display GPx3 loss." (PMID 32781581, 2020). "In hepatocellular carcinoma, almost 80% of tumor samples exhibited GPx3 hypermethylation, leading to its markedly reduced mRNA and protein levels, suggesting its potential as a broad-spectrum tumor screening marker due to its measurable presence in plasma." (PMID 39594513, 2024). "The levels of GPx1 and 2 and Prdx1, 3, and 5 in hepatoma cells were increased compared to hepatocyte-like cells, while GPx3 was markedly reduced." (PMID 37189460, 2023). "GPx3 is also down-regulated in hepatocellular carcinoma and esophageal squamous cell carcinoma through promoter hypermethylation, which may lead to cancer development and progression." (PMID 34926458, 2021). "The methylation of the GPx3 promoter was also observed in hepatocellular carcinoma (HCC) tissue and gastric carcinoma, possibly leading to subsequent carcinogenesis and cancer cell progression." (PMID 32571353, 2020). "Compared to healthy controls, GPx3 expression is also lower in both the plasma and tumor tissue of non-small-cell lung cancer (NSCLC), glioblastoma, and hepatocellular carcinoma (HCC) patients." (PMID 32781581, 2020).
colorectal cancer (15 papers, 2011 to 2026). A primary or metastatic malignant neoplasm that affects the colon or rectum. "In a mouse model of azoxymethane/dextran sodium sulfate-induced colorectal cancer, deficiencies in antioxidant genes such as GPx3 increase the number of tumors in mice." (PMID 28441719, 2017). "Conversely, in certain cancers, GPX3 methylation leads to reduced expression, in colorectal cancer, GPX3 promoter methylation serves as a predictor of sensitivity to platinum-based treatments." (PMID 40092686, 2025). "In colorectal cancer, increased GPX3 expression resulted in increased resistance to oxaliplatin and cisplatin." (PMID 35906899, 2023). "We found that knockdown GPX3 reduced wound healing ability and transmembrane migration ratio of ovarian and colorectal cancer cells." (PMID 36845676, 2023). "In colorectal cancer, GPX3 methylation reduced GPX3 expression and increased oxaliplatin and cisplatin sensitivity." (PMID 37790850, 2023). "We suggested for the first time that downregulation of mitochondrial genes, including ETHE1, SQOR, TST, and GPX3, would help colorectal cancer cells to produce more energy under hypoxic conditions through mechanisms that are different from “Warburg Effect”." (PMID 34249670, 2021). "Decreased plasma GPx3 expression in cancer patients has been reported for several tumor types, including uterine and colorectal cancers." (PMID 32781581, 2020). "There are also studies demonstrating that GPX3 expression is increased in certain cancers, including clear cell adenocarcinoma, colorectal carcinoma, ovarian cancer and leukemia." (PMID 33050144, 2020). "GPX3 was found to be downregulated in the plasma of breast, gastric, and colorectal cancer patients." (PMID 24790704, 2014). "A number of studies have shown GPX3 activity to be downregulated in patients with breast, gastric and colorectal cancers." (PMID 22017790, 2011). "In light of previous scientific inquiries, it’s compelling to mention that many of the genes within this list of 10, specifically CAV1, DAPK1, GPX3, IGFBP6, TIMP1, GADD45B and ENO2 have been found associated intimately with colorectal cancer, as documented by several research studies." (PMID 38501104, 2024). "Similarly, it was found that colorectal cancer cells with low GPx3 expression are also more sensitive to chemotherapies such as oxaliplatin and cisplatin, while cells with high GPx3 expression have increased resistance to platinum-based therapy." (PMID 32781581, 2020). "However, several studies conducted on tissue as well as blood/serum samples have shown that levels of the antioxidant enzyme GPX3 are decreased in a number of human cancers, including breast, gastric, prostrate and colorectal cancer; a seemingly contradictory effect." (PMID 22017790, 2011). "Four Se markers, namely total-Se, the circulating selenoproteins GPx3 and SELENOP, and autoantibodies to SELENOP, were analyzed in participants of the ongoing Colorectal Cancer Study of Austria (CORSA)." (PMID 40435558, 2025). "A study found that patients with colorectal cancer have significantly lower levels of GPX3 gene expression than those without the disease." (PMID 38042786, 2023). "However, in colorectal cancer cell culture studies, knock-down of GPx3 failed to induce compensatory increases in GPx1 or GPx2." (PMID 32781581, 2020).